CD47 (CD47 molecule)
Diseases named in the same sentence as CD47 in open-access papers (continued):
Sharing a sentence is not in itself a finding about the gene and the disease.
cancer (continued). "Therefore, it would be interesting to determine whether miR-200a targets CD47 in parallel to PD-L1 to exert regulatory effects on immune checkpoints in cancer." (PMID 32149101, 2020). "Interestingly, however, it has recently been observed that CD47 inhibition may result in cancer cell resistance to chemotherapy through escape to senescence." (PMID 32322199, 2020). "In addition to cancer, all immune cells upregulate CD47 upon pathogen invasion." (PMID 32882841, 2020). "However, aberrant cells, such as cancer cells, may also exploit this pathway by (over)expressing CD47 and thus escaping immune-mediated destruction." (PMID 33162986, 2020). "Therapies inhibiting CD47-SIRPα interaction are expected to work in two ways: firstly, by activation of adaptive immunity, resulting in cytotoxic anti-tumor responses, and secondly, by activation of innate immunity, therefore promoting cancer cells destruction by macrophages." (PMID 33384022, 2020). "It is not by coincidence that cancer cells are also associated with increased CD47 expression." (PMID 32882841, 2020). "In addition, special attention should be paid to CD47, overexpressed on tumoral cells and reliable for the immune-escaping assets of cancer which depends on the interaction with signal regulatory protein-α (SIRP-α) manifested by macrophages and dendritic cells." (PMID 32937963, 2020). "However, several recent studies on the use of anti-CD47 in both cancer and infections contradict this speculation." (PMID 32882841, 2020). "The knockdown of CD47 suppressed certain stem-like properties of cancer cells, such as self-renewal and chemoresistance, suggesting that targeting CD47 could not only activate the phagocytosis of macrophages but also could be used to enhance treatment against CSCs." (PMID 32244422, 2020). "In summary, these results demonstrated that CD47/SIRPα blocking peptides, pep-20 and its derivate, could serve as promising candidates to promote macrophages-mediated phagocytosis and immune response in cancer immunotherapy." (PMID 33020240, 2020). "Therefore, CD47 is suggested as a prominent new target in the cancer immunotherapy 9,19." (PMID 32226539, 2020). "In cancer, multiple inhibitory checkpoints may be modulated, including programmed death ligand-1/2 (PD-L1/2), CD47, Galectin 9, and TNFRSF6B, for which ligands expressed on T cells or APCs may act synchronously or sequentially to promote overall suppression of the immune responses." (PMID 31750244, 2019). "Disruption of the CD47/SIRPα axis with specific mAbs may promote cancer cell elimination by macrophages, and it is a potential immunotherapeutic strategy recently described for different cancers, including SCLC and NSCLC." (PMID 32082304, 2019). "Knockdown of CD47 suppressed certain stem‐like properties of cancer cells, such as self‐renewal and chemoresistance, suggesting that targeting CD47 could not only active the phagocytosis of macrophages, but also be refined into a potent supplement in treatment against CSCs." (PMID 30741466, 2019). "In addition, targeting CD47 inhibits the proliferation of breast CD44highCD24low cancer stem cells." (PMID 30814491, 2019). "Thus, therapeutic targeting of cancer cells was observed with CD47 blockade." (PMID 32038992, 2019). "Moreover, MYC activates expressions of CD47 and PD-L1 in cancer cells." (PMID 29416769, 2018). "Thus, hypoxic cancer cells evade innate immunity through HIF-1α-dependent expression of CD47." (PMID 30061885, 2018). "In 2015, as part of the Reproducibility Project: Cancer Biology, we published a Registered Report that described how we intended to replicate selected experiments from the paper “The CD47-signal regulatory protein alpha (SIRPa) interaction is a therapeutic target for human solid tumors “." (PMID 28100392, 2017). "Thus, anti-CD47 therapy may provide a complementary way to target the TICs population to prevent metastasis and cancer recurrence." (PMID 28380460, 2017).
cancer (continued). "Thus, CD47-CAR-T cells can be used to target cancer stem cells." (PMID 29065481, 2017). "However, the mechanism by which anti-CD47 antibodies affect cancers remains unclear and controversial, and this limits the development of these antibodies as therapeutic agents." (PMID 28977832, 2017). "Also, while the prognostic significance of CD47 in PCa is unknown, our data suggest that CD47 may be a good target for this type of cancer." (PMID 28403150, 2017). "Also, CD47 expression on cancer stem cells (CSCs) implies its role in cancer recurrence." (PMID 28077173, 2017). "Therefore, the conclusion is that anti-CD47 antibody treatment not only enabled macrophage phagocytosis of cancer cells but could also initiate an antitumour cytotoxic T cell immune response." (PMID 27212807, 2016). "Therefore, interruption of the ability of CD47 by anti-CD47 antibodies might have a therapeutic effect to enhance cancer cell phagocytic uptake." (PMID 25918716, 2015). "Indeed, elevated CD47 expression is strongly correlated with resistance to anti-cancer therapy." (PMID 26486085, 2015). "However, many types of cancer cells express higher quantities of CD47 compared to normal cells." (PMID 25688334, 2015). "Antibodies to block CD47 may prove useful in cancer treatments in future." (PMID 29147386, 2014). "Additional experiments in human cancer cells and investigation of direct molecular interactions between DNAJC13 and CD47 trafficking machinery would strengthen the translational potential of these findings." (PMID 41601654, 2026). "We first established CD47 knockout (KO) cancer cell lines using CRISPR-Cas9 and confirmed effective reduction of both CD47 mRNA and protein levels." (PMID 41601654, 2026). "However, neither ERK inhibitor nor PPARγ agonist could influence CD47 expression in lamin-deficient cancer cells." (PMID 40708945, 2025). "Much effort has been directed at engineering molecules that bind to the CD47 ECD to increase T cell and macrophage killing of cancers." (PMID 41511354, 2025). "Exosomes derived from HPV(+) cancers carry immunomodulatory molecules such as PD-L1, TGF-β, CD47, and miR-1468-5p, which contribute to immune evasion by suppressing cytotoxic T cell activity and promoting lymphangiogenesis." (PMID 41154440, 2025). "This was confirmed by a pan-cancer analysis of the TCGA cohort to evaluate the MSLN and CD47 mRNA expression levels across 30 cancer entities." (PMID 40402266, 2025). "Conversely, blocking this CD47 signaling on mouse and human cytotoxic CD8 T cells increases their antigen-dependent killing of cancer cell targets." (PMID 40943300, 2025). "Robust CD47 protein expression was validated in EOC cells by MPFC and is particularly prominent on tissue-derived cancer cells (median MFI ratio 41.8)." (PMID 40402266, 2025). "PPAB001 disrupts the interaction between CD47 and its receptor SIRPα, as well as between CD24 and Siglec-10, thereby promoting the phagocytic activity of macrophages against cancer cells." (PMID 40330466, 2025). "PPAB001 is a bispecific antibody fusion protein designed to simultaneously target and block CD47 and CD24, two critical immune checkpoints that inhibit macrophage-mediated phagocytosis of cancer cells." (PMID 40330466, 2025). "Subsequently, we analysed the expression levels of these genes across 33 types of cancer and found that AXL, MERTK, TYRO3, CD24, HAVCR2 and CD47 exhibited higher expression levels, while TIMD4 and HAVCR1 showed relatively lower expression." (PMID 40576208, 2025). "Gene groups linked to efferocytosis, including Tyro3, Axl, MerTK, Gas6, BAI-1, CX3CL1, CD31, CD47, Rac1, and the TIM family, represent significant targets for prospective cancer therapies." (PMID 39911848, 2025). "Another study demonstrated that AFP interacts with HuR to enhance the translocation of CD47 to the cell membrane, upregulating the localization of CD47 on the surface of HCC cells and consequently inhibiting macrophages from phagocytizing these cancer cells." (PMID 40430002, 2025).
cancer (continued). "Osimertinib, a third‐generation of EGFR TKI, induced higher CD47 expression in EGFRmut NSCLC HCC827 and NCI‐H1975 cells via NF‐κB signaling, and it also reduced PD‐L1 expression in cancer cells." (PMID 40859900, 2025). "Some cancer cells express “don't eat me” signal ligands such as CD47 and CD24, which can be recognized by TAM receptors such as SIPR1a (for CD47) and SIGLEC10 (for CD24), effectively blocking the attack from TAMs." (PMID 40083710, 2025). "Membrane proteins such as CD47 on the surface of red blood cells are known to inhibit phagocytosis, while MCF‐7 cancer cells express adhesion proteins on their membranes that bind to other cancer cells." (PMID 40007074, 2025). "In this work, we provided preclinical evidence supporting the efficacy of combining TKIs with anti-CD47 mAb in both blood and solid ALK-positive cancers." (PMID 39767726, 2024). "Appealing targets for immunomodulation by VHHkappa conjugates include OX40, CD25, GITR, CD47 and CD73.7,8,48 Our findings support the pursuit of bispecific antibody engagers to target additional cancer-specific and immunomodulatory markers." (PMID 39149504, 2024). "A highly significant positive correlation was also observed between CD47 and IFT57 mRNA expression across the 1156 cell lines in the Cancer Cell Line Encyclopedia (CCLE) (p = 4.6 × 10−36)." (PMID 39201643, 2024). "CD47 antagonists inhibit cancer growth by restoring and enhancing APC-mediated innate and adaptive anti-cancer immunity." (PMID 38474078, 2024). "IF results acquired from consecutive sections of BC tissue in patient 2 showed robust CD47 and CD24 protein expression by cancer cells, indicating redundancy of the two membrane-bound “don’t-eat-me” signals." (PMID 38971872, 2024). "However, in the future, by exploring the impact of CD47 degradation in lysosomes on other signaling pathways and biological functions, the development of interventions targeting the CD47 lysosomal degradation process holds significant promise for enhancing the efficacy of cancer immunotherapy." (PMID 38370407, 2024). "A cancer stem cell (CSC) sub-cluster was selected among 12 cancer cell sub-clusters due to an enrichment in stem cell marker expression, such as CD44, CD98, CD47, and CD276." (PMID 39409886, 2024). "In summary, the simultaneous inhibition of CD47 and VEGF using SIRPα-VEGFR1 successfully stimulated the immune response of the host against cancer recurrence, leading to a significant extension in overall survival." (PMID 38532108, 2024). "CD47 and CD24 function as innate ICs, diminishing the phagocytic action of macrophages on cancer cells in a synergistic manner." (PMID 38971872, 2024). "Preliminary data from preclinical mouse models have shown anti-CD47 therapy to be very effective in treating breast, ovarian, and GBM cancers." (PMID 39194679, 2024). "We observed that the M2-like TAMs upregulated the expression of CD24, CD47 and ICAM1 (markers enriched in cluster C6 cancer cells) in MHCC7L HCC cells." (PMID 38169544, 2024). "Herein, a peptide-antibody combo-supramolecular in situ assembled CD47 and CD24 bi-target inhibitor (PAC-SABI) is described, which undergoes biomimetic surface propagation on cancer cell membranes through ligand-receptor binding and enzyme-triggered reactions." (PMID 38971872, 2024). "Several anti-phagocytic “don’t eat me” signals, such as CD47, CD24, and MHC I, have been identified, the blockade of which can unleash phagocytosis toward cancer cells." (PMID 39766137, 2024). "Analogous to CD47–SIRPα interaction, CD24 on cancer cells inhibits phagocytosis by binding to macrophage Siglec-10." (PMID 38831013, 2024). "Through ceRNA with miR-519d-5p, KCTD21-AS1 regulates the expression of CD47 and TIPRL, which further regulates macrophage phagocytosis and cancer cell autophagy." (PMID 38383737, 2024).
cancer (continued). "Similarly, another study revealed that pyroglutamate formation catalyzed by isoQC at the N-terminus is required for CD47–SIRPα binding, suggesting that isoQC is an essential regulator of the CD47–SIRPα axis and is required for efficient phagocytic cell-mediated clearance of cancer cells." (PMID 38426113, 2024). "Intriguingly, we also found that the cancer stem cells (CSC) score, calculated using common CSC markers (EPCAM, CD24, KRT19, SOX9, PROM1, CD44, THY1, CD47), was significantly higher in the EMT-subtype." (PMID 39095854, 2024). "Here the authors report the design of a peptide-antibody combo-supramolecular in situ assembled CD47 and CD24 bi-target inhibitor that enhances the phagocytic ability of macrophages and improves response to anti-PD-1 in preclinical cancer models." (PMID 38971872, 2024). "The high expression levels of CD47 and TNFRSF9 in cancer cells and their correlation can be demonstrated through multiple immunofluorescence staining." (PMID 38720108, 2024). "Phagocytosis checkpoints like CD47, CD24, MHC-I, and PD-L1 play a critical role in cancer immunotherapy by acting as escape signals from immunogenic cells, thereby weakening the immune activity against tumors." (PMID 39726713, 2024). "We found CD47 had strong correlation with CD274, LAG3, IDO1 and TNF receptor superfamily in pan-cancer(r > 0.2, p < 0.05)." (PMID 38720108, 2024). "Of note, cluster C6 cancer cells mainly came from two patients (P8 and P9), in which more than 90% of cancer cells were demarcated with triple expression of CD24/CD47/ICAM1." (PMID 38169544, 2024). "Furthermore, our study suggests that CD47 upregulation may represent a novel mechanism of resistance, and targeting this upregulation could significantly restore phagocytic activity, facilitating the eradication of resistant ALKi cancer cells." (PMID 39767726, 2024). "In studies that jump‐started interest in CD47 targeting, blocking antibody B6H12 enlarged macrophage activity against cancer cells while subsequently stimulating T cells." (PMID 38362603, 2024). "Moreover, our hypothesis considered the possibility of redirecting TAMs activity against ALK-positive tumors, particularly through the restoration of phagocytosis of cancer cells with CD47.DEMs blockade, which would eventually prime CTL through the presentation of ALK peptides." (PMID 39767726, 2024). "The strong enhancement of SG635-SF antitumor effect was thus demonstrated to be CD47-dependent, suggesting the efficacy of SG635-SF in the treatment of CD47-positive cancers." (PMID 38832992, 2024). "Treatment with the anti-CD47 nanobody fragments resulted in a notable increase in the number of phagocytosed MCF7 and U937 cancer cells." (PMID 38247566, 2024). "CD47 binds to the SIRRP-α receptor on the surface of phagocytes and transmits the “Don’t eat me” signal of innate immune response, thereby inhibiting cancer cell clearance." (PMID 39135122, 2024). "Using chromatin immunoprecipitation (ChIP) approaches along with the analysis of ChIP-Seq cancer datasets, we identified the transcription factor NRF-1 which binds at multiple sites within the proximal CD47 promoter region." (PMID 39742254, 2024). "The strong coexpression of CD47 and IFT57 mRNAs across carcinomas from multiple tissues suggests that engagement of these or other nearby enhancers by oncogenic transcription factors induces the expression of both genes." (PMID 39201643, 2024). "Therefore, CD47 could be a potential target for cancer immunotherapy." (PMID 37545625, 2023). "Emerging evidence has identified innate immune checkpoints and pattern recognition receptors, such as CD47 and Toll-like receptor 7 (TLR7), as promising therapeutic targets for cancer treatment." (PMID 37049910, 2023). "CD47 is known as a “don’t eat me signal” and binds to signal-regulatory protein alpha (SIRP-α) expressed on macrophages, allowing cancer cells to escape phagocytosis by macrophages." (PMID 36768216, 2023).
cancer (continued). "Co-inhibitory immune checkpoints, such as PD1, CD47, CTLA4 and LAG3, are highly expressed on T cell in a variety type of cancers, leading to attenuated T cell responses and ultimately immune evasion of cancer cells." (PMID 38035111, 2023). "To explore the role of CD47 in GC development in mouse livers, we knocked down CD47 in MNK45-luc2-labeled cancer cells and injected them into BALB/c nude mouse livers." (PMID 36860925, 2023). "Along with the well-known PD-1, PD-L1, and CTLA-4, and in addition to SIRPα/CD47, TIM-3 has emerged as a promising target in cancer immunotherapy." (PMID 36829496, 2023). "Studies in the past decades provided ample data that cancer plasticity can be manifested also in the expression of a vast array of immune cell genes; best-known examples are PDL1/CD274, CD47, or IDO, and we termed it immunogenic mimicry (IGM)." (PMID 36754910, 2023). "The adenosine A2A and A2B receptors, CD47-SIRPα, TIM-3, LAG-3, TIGIT, and VISTA are targets that also contribute to cancer immunoresistance and have been considered for clinical trials." (PMID 36829496, 2023). "Hence, CD47 could be a promising candidate for target therapy in future cancer treatment." (PMID 37373873, 2023). "Thus, cancer cells may escape immune cells by upregulation of CD47 expression." (PMID 36598153, 2023). "Therefore, the targeting of CTLA-4 and PD-1 negative immune checkpoints-based immune suppression pathway along with some other important regulatory checkpoints such as Siglec factors and CD47-SIRPα may contribute to the upgrade of immune responses against cancer cells." (PMID 36109471, 2023). "Phagocytosis increased when M2‐like macrophages were co‐cultured with cancer cells, particularly in the case of paired DEMs blockade (i.e. anti‐CD24 + anti‐CD47) combined with Rituximab." (PMID 37654003, 2023). "Here, we further tested the effect of 6-OAU with the CD47-blocking antibody, B6H12, in cancer cell phagocytosis by bone marrow-derived macrophages (BMDMs)." (PMID 37709767, 2023). "Cell surface CD47 was shown to bind to SIRP alpha protein on the macrophage surface, which initiates a “don’t eat me” signal, an important contributor to cancer cell immune evasion." (PMID 37894298, 2023). "CD47, a cell surface protein, has been identified as a crucial regulator of the TME and a potential therapeutic target for cancer therapy." (PMID 38188674, 2023). "In this respect, the cancer cell-specific peptides CDX (FKESWREARGTRIERG) and CREKA (Cys-Arg-Glu-Lys-Ala) were introduced to the N-terminal of CD47, and parent cells were transfected with a plasmid coding for the peptide–CD47 fusion to produce modified EVs." (PMID 37686050, 2023). "In TCGA database, the overall survival of all cancer patients was favored with a high level of CALR and a low level of CD47." (PMID 36943734, 2023). "Overall, our in vitro, in vivo, and patient data is consistent in that Kaiso plays a regulatory role in THBS1, CD47, and SIRPA, which are each well documented for cancer to evade immune surveillance." (PMID 37190208, 2023). "The interaction between CD47 and SIRP-α, called self-labeling, prevents the cancer cell's engulfment by macrophage cells and includes the ‘don’t it me’ signals." (PMID 38017494, 2023). "Of note, NK cells in LRT 8 days groups are located closer to cancer cells and in higher percentages than other immune cells except CD8+ T cells, probably due to the regulatory effect of low-expressed CD47 on NK cells." (PMID 37951973, 2023). "CD47 regulates CD8+ T cell activation, proliferation, and fitness in a context-dependent manner, including cancer." (PMID 37275901, 2023). "Mounting evidence confirmed that several potential candidates were overexpressed in certain cancers and contributed to glycolysis, including FUBP1, HIF-1α, and CD47." (PMID 37626036, 2023). "In summary, CD47 plays a critical role in regulating the TME and evading the immune system, making it an attractive therapeutic target for cancer treatment." (PMID 38188674, 2023).